CLDN3 (claudin 3)
Description:
Barrier-forming claudin. Plays a major role in tight junction-specific obliteration of the intercellular space, through calcium-independent cell-adhesion activity.
Synonyms: hRVP1; C7orf1; CPETR2; RVP1; CPE-R2
Tractability: Antibody: UniProt places it where antibodies can reach, with high confidence; its Gene Ontology location is reachable by antibodies, with high confidence; UniProt predicts a signal peptide or a membrane-spanning region. PROTAC: ubiquitination databases record sites on it.
Gene: Protein-coding gene on chromosome 7 (73,768,997 to 73,770,270, reverse strand). Ensembl gene ENSG00000165215.
Subcellular location: Cell junction, tight junction; Cell membrane
Subcellular location (Human Protein Atlas): Cell Junctions
Pathways (Reactome):
Cell-Cell communication: Tight junction interactions
Gene Ontology:
Molecular function: cell-cell adhesion mediator activity; identical protein binding; protein binding; structural molecule activity; transmembrane signaling receptor activity
Biological process: actin cytoskeleton organization; bicellular tight junction assembly; cell junction assembly; cell-cell junction maintenance; negative regulation of cell migration; negative regulation of cell population proliferation; negative regulation of gene expression; negative regulation of phosphate transmembrane transport; positive regulation of cell migration; positive regulation of gene expression; positive regulation of wound healing; regulation of cell morphogenesis; regulation of membrane permeability; regulation of transepithelial transport; response to hypoxia; retinal pigment epithelium development; cell adhesion; cell junction maintenance; epithelial cell morphogenesis; establishment of endothelial blood-brain barrier; maintenance of blood-brain barrier; calcium-independent cell-cell adhesion; response to ethanol; response to Gram-positive bacterium
Cellular component: apical junction complex; bicellular tight junction; cell junction; cell-cell junction; plasma membrane; protein-containing complex; tight junction; membrane; apicolateral plasma membrane; lateral plasma membrane
Genetic constraint (gnomAD): Loss-of-function variants: 6 observed, 15.81 expected, observed/expected ratio (o/e) 0.38, 90% interval 0.21 to 0.75. The upper end of that interval is the gene's LOEUF score, 0.75, which puts it in group 3 of 6, group 1 being the genes least tolerant of losing a copy. Missense variants: 248 observed, 316.88 expected, observed/expected ratio (o/e) 0.78, 90% interval 0.7 to 0.87. Synonymous variants: 145 observed, 156.11 expected, observed/expected ratio (o/e) 0.93, 90% interval 0.81 to 1.07.
Homologues: Orthologues: chimpanzee CLDN3 (100% identical), macaque CLDN3 (96% identical), mouse Cldn3 (91% identical), dog CLDN3 (90% identical), rat Cldn3 (90% identical), guinea pig CLDN3 (80% identical), zebrafish cldne (60% identical). Paralogues in human: CLDN4 (66% identical), CLDN9 (63% identical), CLDN6 (58% identical), CLDN5 (55% identical), CLDN1 (49% identical), CLDN8 (47% identical), CLDN17 (46% identical), CLDN7 (45% identical), CLDN19 (43% identical), CLDN14 (42% identical), CLDN2 (37% identical), CLDN15 (37% identical), and 10 more.
Diseases named in the same sentence as CLDN3 in open-access papers:
CLDN3 is named in the same sentence as 165 diseases in open-access papers, as found by Europe PMC text mining. Sharing a sentence is not in itself a finding about the gene and the disease. The quoted sentences say what the papers report.
ovarian carcinoma (82 papers, 2005 to 2025). A malignant neoplasm originating from the surface ovarian epithelium. "In ovarian cancer, loss of repressive histone methylations, including H3K27me3 and H4K20me3, is associated with increased expression of CLDN3 and CLDN4." (PMID 38731853, 2024). "A significant association between CLDN3 upregulation and tumor progression had also been reported for breast and ovarian cancer." (PMID 39658782, 2024). "In ovarian cancer cells, CLDN3 and CLDN4 loss of expression promotes epithelial-mesenchymal transition (EMT), suggesting a central role in epithelial phenotype." (PMID 36614243, 2023). "Down regulation of claudin-3 was associated with reduced growth and proliferation and a significantly increased number of apoptotic cells in ovarian cancer." (PMID 26083392, 2015). "Low CLDN3 protein expression was associated with a trend toward poorer survival in an analysis of 115 primary ovarian carcinomas." (PMID 23805314, 2013). "For example, mutation of a PKA phosphorylation site in claudin-3 has been shown to lead to an increased cytoplasmic localization in ovarian cancer." (PMID 21789222, 2011). "A number of protein-coding genes are overexpressed in ovarian cancer because of loss of DNA methylation, including maspin, claudin-3 and claudin-4." (PMID 21694727, 2011). "Using high-throughput technologies to analyze genetic fingerprints of ovarian cancer, we have discovered extremely high expression of the genes encoding the proteins claudin-3 and claudin-4." (PMID 20598131, 2010). "In addition to DNA methylation, our group reported that loss of repressive histone methylations, including H3K27me3 and H4K20me3, is also associated with the overexpression of claudin-3 and claudin-4 in ovarian cancer and claudin-4 in gastric cancer." (PMID 24009024, 2013). "Furthermore, these findings are in conflict with the association of high claudin-3 expression with poor prognosis of ovarian cancer patients, including the shorter survival of patients previously reported by our group." (PMID 24009024, 2013). "We hypothesized that loss of CLDN3 or CLDN4 activates an EMT in ovarian cancer cells." (PMID 23805314, 2013). "Preclinical studies have also yielded antibodies against CLDN4 (to deliver toxins to pancreatic and ovarian cancer cells) and CLDN3." (PMID 40687428, 2025). "Knocking down ZDHHC12 disrupts CLDN3 membrane targeting/stability and impairs ovarian cancer tumorigenicity, highlighting ZDHHC12 as a therapeutic target." (PMID 40977744, 2025). "In summary, ovarian cancer exhibits a pattern of claudin upregulation (CLDN3, CLDN4, CLDN7, CLDN9) that supports tumor growth, dissemination, and chemoresistance." (PMID 40687428, 2025). "ZDHHC12 mediates CLDN3 palmitoylation at three juxtamembrane cysteine residues, critical for ovarian cancer progression." (PMID 40977744, 2025). "In ovarian cancer, zDHHC12 mediates S-palmitoylation of CLDN3 at C181, C182, and C184, which contributes to its proper localization and stabilization on the plasma membrane." (PMID 38415253, 2024). "Integrating these molecular insights with the broader application of CAR-T therapy underscores the potential for targeting CLDN3 in ovarian cancer treatment." (PMID 39033780, 2024). "The overexpression of CLDN3 in ovarian cancer, contrasted with its low levels in normal tissues and benign conditions, positions it as a distinct antigen for CAR-T cell targeting." (PMID 39033780, 2024). "Regulation of claudin 3 protein (CLDN3) (gene: CLDN3) in ovarian cancer cells is a complex process influenced by genetic and epigenetic factors." (PMID 39033780, 2024). "Knocking out zDHHC12 in ovarian cancer significantly inhibits the precise membrane localization and protein stability of CLDN3, as well as tumor occurrence in ovarian cancer cells." (PMID 39563863, 2024). "zDHHC12 was shown to mediate the S‐acylation of membrane claudin‐3 (CLDN3), a tight junction protein that positively correlates with ovarian cancer progression." (PMID 39429488, 2024).
ovarian carcinoma (continued). "In an ovarian cancer cell line, CLDN3 or zDHHC12 silencing disrupted CLDN3 S‐acylation and abolished tumorigenesis." (PMID 39429488, 2024). "It has also been reported that ZDHHC12 promotes the stability of CLDN3 by affecting its cell membrane localization, which in turn promotes ovarian cancer progression." (PMID 38821916, 2024). "Through palmitoylation, ZDHHC16 stabilizes the CLDN3 protein and promotes the incidence and growth of ovarian cancer." (PMID 38532349, 2024). "We found that the 5mC levels of CLDN3 were diminished in colon, prostate, and ovarian cancers in comparison to normal and paracancerous tissues." (PMID 39477806, 2024). "Immunohistochemistry analysis revealed that IgGH6 bound to cell surface CLDN3 expressed on ovarian cancers cells, which was localized outside of cell-cell contact regions and readily internalized, undergoing a similar process as observed with C-CPE." (PMID 38371623, 2024). "Other studies have demonstrated that CLDN3 expression was regulated by promoter methylation in esophageal cancer and ovarian cancer cells." (PMID 36614243, 2023). "For instance, an increase in claudin 3 and 4 is relevant to increases in cell invasion, motility, and survival of ovarian cancer cells." (PMID 36714681, 2023). "Expressions of claudin, including claudin-3, -4 and -7, were markedly higher in chemoresistant ovarian cancer cells than in chemo-sensitive ovarian cancer cells." (PMID 35747825, 2022). "Sp1 is reported to bind to the claudin-3 promoter region at −112 to −74 bp in ovarian cancer cells, which is consistent with our result of −147 to 52 bp." (PMID 34831451, 2021). "Similar to our findings in prostate cancer, higher levels of Cldn3 and Cldn4 expression have been observed in aggressive ovarian cancers, than in normal ovarian cells." (PMID 35006480, 2021). "In CRC and hepatocellular carcinoma (HCC), promoter hypermethylation of CLDN3 is correlated with decreased claudin-3 expression, but promoter derepression leads to upregulation in prostate and ovarian cancers." (PMID 34354941, 2021). "Huang and colleagues showed that knocking down CLDN3, using siCldn3, reduced tumor growth in a mouse ovarian cancer model." (PMID 35006480, 2021). "CLDN3 over-expression has been reported in all subtypes of epithelial ovarian cancers, and appeared to enhance angiogenic and invasive properties." (PMID 32664456, 2020). "In a similar manner with our results, claudin-3 and claudin-4 upregulated in 90% of the ovarian cancer cells." (PMID 32091301, 2020). "Recent studies have exploited the CPE mediated targeting of claudin-3 and 4 cancers to target therapy-resistant ovarian cancer, pancreatic, and breast cancer xenografts possessing increased expressions of claudin-3 and -4." (PMID 31861759, 2019). "The carcinomas in SCID pigs were morphologically similar to the original ovarian carcinoma and had the same immunohistochemical phenotype based on expression of Claudin 3, Claudin 4, Cytokeratin 7, p16, and EMA." (PMID 30723704, 2019). "A previous study identified that the promoter of CLDN3 is affected by epigenetic processes through DNA methylation in ovarian cancer cells." (PMID 31040866, 2019). "The claudin-3 promotor is known to possess low DNA methylation and high histone H3 acetylation for its expression in ovarian cancer cells." (PMID 31861759, 2019). "The CLDN3 is overexpressed in various carcinomas including breast, colorectal, gastric, pancreatic, prostate, and ovarian cancer." (PMID 31905631, 2019). "In one of the studies, the possibility of CPE binding claudin-3 as a visualization tool for identifying of micrometastatic chemotherapy-resistant ovarian cancer has been demonstrated." (PMID 31861759, 2019). "Adding to this, knockdown of claudin-3 or claudin-4 in ovarian cancer cells induced resistance to cisplatin by the regulation of Cu transporter CTR1." (PMID 31861759, 2019).
ovarian carcinoma (continued). "Sp1 is a transcriptional factor known to regulate claudin-3 and claudin-4 promoter activity in ovarian cancer." (PMID 31861759, 2019). "Overexpression of claudin-3 and -4 in ovarian cancer cells promotes cancer progression in both mouse and human ovarian cancer xenografts model." (PMID 30728783, 2018). "In ovarian cancer, downregulation of claudin-3/-4 promotes tumor growth and metastasis, while less expression of claudin-3/-4 along with claudin-7 results in high malignancy in breast cancer." (PMID 30728783, 2018). "The overexpression of claudin-3/-4 correlates to ovarian cancer progression with concomitant activation of MMP resulting in increased invasiveness." (PMID 30728783, 2018). "It was shown that claudin-3 inhibition with small interfering RNA reduced the growth and metastasis of ovarian cancer in xenografts model, which strongly supports the cancer-promoting role of claudin-3." (PMID 30728783, 2018). "As an example, human ovarian carcinomas expressing high levels of Claudin 3/4 expression will grow in SCID pigs." (PMID 30560086, 2018). "Studies have shown that the effects of claudin-3 and claudin-4 are more pronounced in ovarian cancer cells." (PMID 30728783, 2018). "In recent years, it has been reported that claudin-3 was highly expressed in ovarian cancers, but hardly detected in normal ovarian epithelium, thereby, claudin-3 was considered to be a promising target for diagnosis and treatment in ovarian cancers." (PMID 28383479, 2017). "A comparable decrease regarding CLDN-3 and -4 gene expression patterns was reported for cultured human ovarian cancer cell lines that show a lower CLDN expression than primary ovarian tumours." (PMID 27690019, 2016). "Claudin-3 and claudin-4 control tumor growth and metastases through their regulation of β-catenin signaling in ovarian cancer xenografts." (PMID 26083392, 2015). "For intratumoral injection, siLuc and siHuR were encapsulated in the lipidoid nanoparticle 98N12-5, which has been previously shown to effectively deliver claudin-3 siRNA in an ovarian cancer xenograft model." (PMID 26314962, 2015). "Additional evidence supporting the suppressive role of CD151-α3β1 integrin complexes in ovarian cancer comes from the loss of tumor-promoting molecules within CD151-deficient TEMM, such as CD9 and claudin-3." (PMID 25356755, 2014). "This is in line with previous studies demonstrating that the expression level of CLDN3 was epigenetically regulated by promoter methylation in esophageal cancer and ovarian cancer cells." (PMID 25277196, 2014). "Our group also have recently demonstrated that the CPGs CLDN3 and CLDN4 are overexpressed in ovarian cancer in association with decreases in repressive histone marks." (PMID 24551595, 2014). "Several members of claudin family including CLDN3, 4, 7 and 10 have been reported to be more highly expressed in ovarian carcinoma compared to normal ovarian surface epithelium." (PMID 23805314, 2013). "The results showed that the effect of claudin-3 or claudin-4 on the sensitivity of ovarian cancer cells to cisplatin is mediated in part by the regulation of the expression of the copper and cisplatin influx transporter CTR1." (PMID 24009024, 2013). "TJ formation and cell adhesion is impaired in claudin-3 and claudin-4 knockdown ovarian cancer cells." (PMID 24009024, 2013). "Claudin-3 and −4 were frequently elevated in various cancers including pancreatic ductal adenocarcinoma, prostate, uterine, ovarian cancer, while hepatocellular and renal carcinomas expressed lower levels of claudins-4 and −5." (PMID 23591077, 2013). "Especially, CPE is effective in chemoresistant/recurrent ovarian cancer based on the high expression of claudin-3 and claudin-4 in chemoresistant/recurrent ovarian tumors." (PMID 24009024, 2013). "Among claudin proteins, claudin-3 and claudin-4 have been shown to be highly upregulated in ovarian carcinoma compared to normal ovarian surface epithelium in several studies." (PMID 24009024, 2013).
ovarian carcinoma (continued). "Because of their consistent overexpression in ovarian cancer, claudin-3 and claudin-4 have been suggested as potentially useful biomarkers for the detection and diagnosis of ovarian cancer." (PMID 24009024, 2013). "In contrast to the roles of claudin-3 and claudin-4 in ovarian cancer cells, claudin-1 promotes EMT in human liver cells, supporting the notion that the role of claudins in EMT is tissue-specific." (PMID 24009024, 2013). "Because of the frequent dysregulation of claudin-3 and claudin-4 in ovarian cancer cells, the role of these claudins has mainly been reported in ovarian cancer." (PMID 24009024, 2013). "Previous studies have shown that claudin-7 is frequently upregulated in epithelial ovarian cancer (EOC) along with claudin-3 and claudin-4." (PMID 21789222, 2011). "We have previously documented that the 2008 human ovarian cancer cells express claudin 3 and 4 at levels that are readily detectable by Western blot analysis." (PMID 21303546, 2011). "Claudin-3 and -4 expression was examined with rt-PCR and flow cytometry in multiple primary ovarian carcinoma cell lines." (PMID 20598131, 2010). "Claudin-3 and claudin-4 are tight junction proteins overexpressed in ovarian carcinomas, the most lethal gynecologic malignancy in the United States." (PMID 20598131, 2010). "Our results established, to our knowledge for the first time, that the CPE peptide is capable of specifically targeting chemotherapy resistant ovarian carcinoma cells overexpressing the CPE receptors claudin-3 and claudin-4." (PMID 20598131, 2010). "For example, in ovarian cancer, claudin-3 and claudin-7 expression has been shown to be inversely correlated with survival." (PMID 19619303, 2009). "Another independent study found claudin-1, claudin-3 and claudin-7 up-regulation together in ovarian cancer effusions predicts poor progression-free and overall survival." (PMID 19440550, 2009). "In particular, we and others have shown that claudin-3 and claudin-4 are elevated in ovarian cancer." (PMID 19619303, 2009). "Claudin-3 and -4 have emerged as proteins commonly elevated in ovarian cancer, but because they are integral membrane proteins, they had not previously been suggested as serum markers." (PMID 19619303, 2009). "Another gene, claudin 3 (CLDN3), has been found to be highly expressed at gene and protein levels and thus has been suggested as a reliable marker of ovarian cancer." (PMID 19426511, 2009). "Previous studies have shown that Claudin-1, Claudin-3, Claudin-4 and Claudin-7 proteins are highly expressed in ovarian carcinoma." (PMID 18781153, 2008). "In ovarian cancer, for example, where both CLDN3 and CLDN4 are highly up regulated and where intraperitoneal therapy is possible, CPE treatment is certainly an interesting possibility." (PMID 16836752, 2006). "CLDN9 is a tight junction protein normally limited in adult tissues, but it is expressed in ovarian cancer cells and shares homology with CLDN3/4, meaning it might also bind the C. perfringens enterotoxin." (PMID 40687428, 2025). "This complex regulatory landscape results in CLDN3’s overexpression in epithelial ovarian cancer (EOC), and ovarian epithelial inclusion cysts may potentially serve as a marker for malignancy but also as a potential target for immunotherapy." (PMID 39033780, 2024). "Moreover, epigenetic modifications, such as DNA methylation and histone alterations, are significant in regulating the CLDN3 promoter in ovarian cancer cells." (PMID 39033780, 2024). "In ovarian cancer, the membrane protein claudin-3 (CLDN3) promotes tumorigenesis and progression." (PMID 37161425, 2023). "In ovarian cancer, the biological effect of CLDN3 expression appears to be tumor specific." (PMID 36614243, 2023). "Additionally, three proteins previously shown to be associated to ovarian cancer prognosis were added from the literature (i.e. CT45, CDK1 and CLDN3)." (PMID 36544142, 2022).